BMX (BMX non-receptor tyrosine kinase)
Diseases named in the same sentence as BMX in open-access papers (continued):
Sharing a sentence is not in itself a finding about the gene and the disease.
cancer (continued). "However, knockdown of BMX greatly sensitises cancer cells to standard chemotherapeutic agents." (PMID 41213918, 2025). "Furthermore, BMX may also be an important biomarker for survival dependency in specific cancer types." (PMID 26909357, 2015). "This study also emphasized the role of BMX in immune cell infiltration, such as B cells, CD4+ T cells, CD8+ T cells, neutrophils, macrophages, and dendritic cells in certain cancers." (PMID 39347140, 2024). "According to TIMER, GEPIA, and UACLAN; five cancers (BRCA, COAD, LUAD, LUSC, and READ) consistently presented significantly lower levels of BMX expression than normal tissues." (PMID 39347140, 2024). "This study also emphasized the role of BMX in the infiltration of immune cells, such as B cells, CD8+ T cells, CD4+ T cells, macrophages, neutrophils, and dendritic cells, in certain cancers." (PMID 39347140, 2024). "Growing evidence indicates that the signaling proteins of EPHA3 downstream, including PI3K, BMX and STAT3, play crucial roles in tumorigenesis and cancer progression." (PMID 27101199, 2016). "BMX, BMPR1B, BTK, and MDC1 belong to the COSMIC_mut gene set, and CSNK2A2 belongs to the COSMIC_other gene set, while ASH2L belongs to the non-cancer gene set." (PMID 19765316, 2009). "The nonreceptor tyrosine kinase BMX is preferentially expressed in cancer stem cells and cancer cells." (PMID 40103284, 2025). "Overcoming resistance in cancer therapies requires novel strategies, and while BMX has been identified as a promising target, no BMX inhibitors have advanced to clinical trials." (PMID 41213918, 2025). "Importantly, we showed that when BMX activity was suppressed, BAK activity was potentiated and cancer cells became hyper-sensitive to a given dose of drug." (PMID 26909357, 2015). "Therefore, BMX and ARHGAP play wide oncogenic roles on multiple cancers progression." (PMID 31130822, 2019). "As single agents, BMX inhibitors may only have a limited effect on apoptosis as dephosphorylation of BAK alone is not sufficient to trigger BAK activation, but in combination with existing cytotoxic agents would be able to significantly sensitise cancer cells to BAK-dependent apoptosis." (PMID 27140313, 2016).
cardiovascular disease (3 papers, 2020 to 2024). "For instance, BMX has increased expression in cardiac endothelium as a response to ischemia and is being looked at as a possible treatment for cardiovascular diseases." (PMID 34803999, 2021). "But, selectively excluding BMX may not be as necessary since studies have investigated its involvement with inflammatory, cardiovascular diseases, and oncology." (PMID 34803999, 2021).
bacterial infections (1 paper, 2025). "Among the genes, BMX and GRB10 are particularly associated with immune-regulating signaling pathways, while GADD45A is mainly involved in the defense response to bacterial infections." (PMID 40230692, 2025).
infection (1 paper, 2024). The state of being infected such as from the introduction of a foreign agent such as serum, vaccine, antigenic substance or organism. "As the infection progresses, MAP grows within granulomas but the upregulation of the bta-miR-215 and bta-miRNA-146a would control the activation of an excessive pro-inflammatory response by targeting BMX and TRAF6, respectively." (PMID 38167436, 2024).
BMX also shares sentences with these, for which no sentence is quoted: gastric cancer (2 papers); polyp (2); rheumatoid arthritis (2); acute myeloid leukemia (1); bladder urothelial carcinoma (1); cervical (1); colon adenocarcinoma (1); COVID-19 (1); depression (1); esophageal carcinoma (1); gastric cardia adenocarcinoma (1); genetic diseases (1); hematological cancers (1); hematological malignancies (1); invasive breast carcinoma (1); kidney (1); lung squamous cell carcinoma (1); lymphoma (1); Parkinson disease (1); prostate adenocarcinoma (1); rectum adenocarcinoma (1); small lymphocytic lymphoma (1); spinal cord injury (1); stomach adenocarcinoma (1); thyroid carcinoma (1); uterine corpus endometrial carcinoma (1); X-linked agammaglobulinemia (1).